CHI3L1 (chitinase 3 like 1)
Description:
Carbohydrate-binding lectin with a preference for chitin. Has no chitinase activity. May play a role in tissue remodeling and in the capacity of cells to respond to and cope with changes in their environment. Plays a role in T-helper cell type 2 (Th2) inflammatory response and IL-13-induced inflammation, regulating allergen sensitization, inflammatory cell apoptosis, dendritic cell accumulation and M2 macrophage differentiation. Facilitates invasion of pathogenic enteric bacteria into colonic mucosa and lymphoid organs. Mediates activation of AKT1 signaling pathway and subsequent IL8 production in colonic epithelial cells. Regulates antibacterial responses in lung by contributing to macrophage bacterial killing, controlling bacterial dissemination and augmenting host tolerance. Also regulates hyperoxia-induced injury, inflammation and epithelial apoptosis in lung.
Synonyms: CGP-39; GP-39; hCGP-39; GP39; YKL40; YK-40; ASRT7; HC-gp39; HCGP-3P; YKL-40; YYL-40
Tractability: Small molecule: a structure with a bound ligand is known; it has a high-quality binding pocket. Antibody: UniProt places it where antibodies can reach, with high confidence; its Gene Ontology location is reachable by antibodies, with high confidence; UniProt predicts a signal peptide or a membrane-spanning region.
Gene: Protein-coding gene on chromosome 1 (203,178,931 to 203,186,796, reverse strand). Ensembl gene ENSG00000133048.
Subcellular location: Secreted, extracellular space; Cytoplasm; Cytoplasm, perinuclear region; Endoplasmic reticulum
Subcellular location (Human Protein Atlas): Golgi apparatus; Vesicles; Predicted to be secreted
Pathways (Reactome):
Immune System: Neutrophil degranulation
Gene Ontology:
Molecular function: chitin binding; chitinase activity; protein binding; extracellular matrix structural constituent
Biological process: inflammatory response; lung development; positive regulation of angiogenesis; positive regulation of ERK1 and ERK2 cascade; positive regulation of phosphatidylinositol 3-kinase/protein kinase B signal transduction; response to interleukin-1; response to interleukin-6; response to mechanical stimulus; response to tumor necrosis factor; apoptotic process; cartilage development; cellular response to tumor necrosis factor; ERK1 and ERK2 cascade; positive regulation of interleukin-8 production; transforming growth factor beta1 production; carbohydrate metabolic process
Cellular component: extracellular exosome; extracellular region; cytoplasm; endoplasmic reticulum; extracellular matrix; receptor complex; specific granule lumen; perinuclear region of cytoplasm
Genetic constraint (gnomAD): Loss-of-function variants: 30 observed, 40.68 expected, observed/expected ratio (o/e) 0.74, 90% interval 0.55 to 1. The upper end of that interval is the gene's LOEUF score, 1, which puts it in group 4 of 6, group 1 being the genes least tolerant of losing a copy. Missense variants: 464 observed, 477.48 expected, observed/expected ratio (o/e) 0.97, 90% interval 0.9 to 1.05. Synonymous variants: 196 observed, 186.26 expected, observed/expected ratio (o/e) 1.05, 90% interval 0.94 to 1.18.
Homologues: Orthologues: chimpanzee CHI3L1 (99% identical), macaque CHI3L1 (97% identical), rabbit CHI3L1 (85% identical), pig CHI3L1 (84% identical), guinea pig CHI3L1 (83% identical), dog CHI3L1 (79% identical), rat Chi3l1 (76% identical), mouse Chi3l1 (73% identical), Drosophila melanogaster Cht7 (45% identical), Drosophila melanogaster Cht10 (43% identical), Drosophila melanogaster Cht8 (41% identical), Drosophila melanogaster Cht4 (38% identical), and 37 more. Paralogues in human: CHIT1 (53% identical), CHIA (51% identical), CHI3L2 (51% identical), OVGP1 (47% identical), CTBS (21% identical), CHID1 (15% identical).
Diseases named in the same sentence as CHI3L1 in open-access papers:
CHI3L1 is named in the same sentence as 544 diseases in open-access papers, as found by Europe PMC text mining. Sharing a sentence is not in itself a finding about the gene and the disease. The quoted sentences say what the papers report.
asthma (159 papers, 2009 to 2025). "Several studies describe the CHI3L1 gene or YKL-40 protein expression associated with asthma, pointing to their role as potential biomarkers to asthma." (PMID 41154593, 2025). "The promoter SNP (−131C→G) in CHI3L1 is linked to higher serum CHI3L1 levels, asthma susceptibility, bronchial hyperresponsiveness, and lung function indicators." (PMID 40443529, 2025). "Variations in the expression of the CHI3L1 gene, which encodes YKL-40, are also associated with asthma severity, airflow obstruction and airway remodelling." (PMID 38609094, 2024). "Single nucleotide polymorphisms (SNPs) in the Chi3l1 promoter effectively affect the airway expression of Chi3l1 and the severity of asthma." (PMID 39769202, 2024). "Various polymorphisms of Chi3l1, including rs4950928, rs10399931, rs883125, and rs12141494, are important genetic factors for asthma." (PMID 39769202, 2024). "Single nucleotide polymorphism in the CHI3L1 gene (rs4950928) in the American Hutterite population was associated with elevated serum concentrations of YKL-40 in asthma (102.7±2.9 μg/L vs. 87.2 μg/L in healthy controls, P = 0.005)." (PMID 38125621, 2024). "CHI3L1 SNPs are reported to confer risk of asthma development and airway remodeling as well as increased serum IgE and atopy in patient cohorts." (PMID 37575256, 2023). "Studies found that a high-fat diet can induce the expression of the chitinase 3-like 1 gene (CHI3L1), and its expression product is associated with obesity and asthma." (PMID 38292857, 2023). "CHI3L1 is known to regulate tissue injury, repair and inflammation with strong associations in asthma, cancer, diabetes, cirrhosis, and coronary artery disease." (PMID 36572854, 2022). "In an adult case-control study, the serum CHI3L1 encoded protein, called YKL-40, was measured and its levels were found to be significantly elevated in patients with asthma, especially in the group more prone to exacerbations, after stratification." (PMID 33925009, 2021). "CHI3L1 has been strongly associated with diseases including asthma, arthritis, sepsis, diabetes, liver fibrosis, and coronary artery disease." (PMID 32929074, 2020). "(2008) identified CHI3L1, the gene encoding a chitinase-like protein (YKL-40) that had been previously associated with asthma severity, as another susceptibility gene for asthma." (PMID 33324573, 2020). "In the Tsukuba GWAS cohort, the C allele at rs946261 was significantly associated with reduced expression of CHI3L1 mRNA in the lung and with development of asthma (odds ratio (OR) 1.27; P = 0.036)." (PMID 30940096, 2019). "The genotype consisting of the cis-eQTL allele that reduces expression of CHI3L1 was specifically associated with late-onset adult asthma." (PMID 30940096, 2019). "We then used multinomial logistic regression analysis of each of the six clusters to look for an association between the CHI3L1 genotype and specific asthma phenotypes." (PMID 30940096, 2019). "Among the six eQTLs, the presence of the C allele at rs946261, which was significantly associated with reduced expression of CHI3L1 mRNA in the lung (P = 8.30E-09), was associated with the development of asthma (OR 1.27; P = 0.036)." (PMID 30940096, 2019). "Among 34 cis-eQTLs in CHI3L1 in the lung, rs946261 was associated with adult asthma in these Japanese cohorts." (PMID 30940096, 2019). "As promoter SNPs of CHI3L1, rs4950928 and rs10399931 were frequently reported in many association studies of CHI3L1 genetic polymorphisms and asthma." (PMID 30988078, 2019). "This risk allele for development of late-onset asthma was significantly correlated with reduced levels of CHI3L1 expression." (PMID 30940096, 2019). "In contrast to the current study, the original association of CHI3L1 with asthma was found with an increased CHI3L1 mRNA expression." (PMID 30940096, 2019).
asthma (continued). "A meta-analysis of the three independent Japanese cohorts identified one late-onset asthma-associated eQTL, rs946261, in the 3′-untranslated region of CHI3L1 (P = 0.0058)." (PMID 30940096, 2019). "This was the first association study between CHI3L1 and asthma in the southwest Chinese Han population and there are some limitations." (PMID 30988078, 2019). "The objective of this present study was to investigate the association of common variants in CHI3L1 with adult asthma in a southwest Chinese Han population." (PMID 30988078, 2019). "The present study was designed to investigate the association between CHI3L1 polymorphisms and asthma in the southwest Chinese Han population." (PMID 30988078, 2019). "Future studies are necessary and should involve sufficiently powered cohorts of asthma patients and subgrouping by disease phenotype to further understand how genetic variations in CHI3L1 affect the risk for late-onset adult asthma." (PMID 30940096, 2019). "The CHI3L1 genotype was significantly associated with asthma in patients who developed the disease at an older age (OR 1.24; 95% CI 1.07–1.45; P = 0.0058)." (PMID 30940096, 2019). "In conclusion, the loss-of-function CHI3L1 genotype was specifically associated with late-onset asthma that developed at the age of 40 years or older." (PMID 30940096, 2019). "Some other studies also replicated the association between CHI3L1 eQTL and asthma but with the risk allele reversed from the original report." (PMID 30940096, 2019). "CHI3L1 was identified as an asthma susceptibility locus that was also related to airway hyper-responsiveness and decline in lung function in a population of European descent in a genome-wide association study (GWAS)." (PMID 30988078, 2019). "We only successfully performed a meta-analysis of the relationship between rs4950928 and asthma due to the lack of association studies of other variants, including rs10399931, in CHI3L1 with asthma." (PMID 30988078, 2019). "The rs4950928 polymorphism in CHI3L1, as shown in a genome-wide association study (GWAS), is associated with asthma risk, YKL-40 levels in blood, and respiratory function." (PMID 30940096, 2019). "A Genome-wide Association Study (GWAS) has identified that the rs4950928 polymorphism in the CHI3L1 gene is associated with the risk of asthma, circulating YKL-40 level and pulmonary function." (PMID 29233108, 2017). "This was evidenced, for example, by greater expression of TIMP3, an inhibitor of extracellular matrix degradation, and CHI3L1, a secreted glycoprotein also thought to drive tissue remodelling and a known genetic risk factor for asthma severity." (PMID 28061811, 2017). "Our meta-analysis synthesized a total of 1062 cases and 1034 controls from 5 eligible studies to analyze the association between CHI3L1 rs4950928 polymorphism and asthma risk." (PMID 29233108, 2017). "Another study have demonstrated that an association between CHI3L1 rs4950928 polymorphism and asthma is found, although the risk allele was opposite of that reported by Ober." (PMID 29233108, 2017). "After stratified population by ethnicity, analysis indicated that the G allele of CHI3L1 rs4950928 had a reduced risk for asthma in Caucasians." (PMID 29233108, 2017). "Another study on a large cohort of adults with asthma has shown that some SNPs of the CHI3L1 gene are significantly associated with atopy." (PMID 28660216, 2017). "Recently, the relationship between CHI3L1 rs4950928 polymorphism and susceptibility to asthma was increasingly investigated." (PMID 29233108, 2017). "The finding that Th17/Th2 cells express high levels of CHI3L1 is in agreement with the possible pathogenic role of these cells in neutrophilic steroid-resistant asthma since both Th17/Th2 and serum levels of CHI3L1 result to be increased in such disease." (PMID 27826220, 2016).
asthma (continued). "Genetic variation in CHI3L1 was associated with pathological lung function values in adults, and correlated with poor asthma control and inflammatory markers in severe asthmatic children." (PMID 27193312, 2016). "Associations between genetic variation in CHI3L1 and asthma are controversial in the discussion, and the SNP rs4950928 has been extensively studied in this context." (PMID 27193312, 2016). "In fact, genetic variation of CHI3L1 gene associated with its higher expression in serum and with exacerbation of asthma and airways tissue remodelling." (PMID 27826220, 2016). "We studied in a birth cohort of unselected infants the association of SNPs in CHI3L1 and cord blood YKL-40 levels with asthma development." (PMID 27193312, 2016). "It is a weakness that rs4950928 was not genotyped in our study and that we cannot conclude on associations between this extensively studied tag SNP in CHI3L1 and asthma development." (PMID 27193312, 2016). "Our findings are in contrast to those of two previous studies that showed an association between the CHI3L1 (−131 C/G, rs4950928) genotype and the risk of asthma." (PMID 26672955, 2015). "A follow-up study analyzing single nucleotide polymorphisms (SNPs) in the YKL-40/CHI3L1 gene showed a genetic association with increased susceptibility to asthma, increased bronchial hyperresponsiveness, and reduced lung function." (PMID 26542293, 2015). "In humans, mutations in the CHI3L1 gene have been shown to associate with some features of asthma, and increased CHI3L1 concentrations in lung and serum often correlate with disease severity." (PMID 26067998, 2015). "Based on the present findings, it is difficult to be conclusive about a connection between the SNP (−131 C/G, rs4950928) in the CHI3L1 gene and the risk of having asthma." (PMID 26672955, 2015). "Polymorphisms in CHI3L1 as well as the concentration of its corresponding protein YKL-40 in serum has been associated with asthma and pulmonary function." (PMID 24991220, 2014). "Several recent studies have shown that genetic variations of CHI3L1 SNPs have an impact on inter-individual serum YKL-40 levels as well as susceptibilities to atopy, sarcoidosis, asthma, and lung function." (PMID 25203433, 2014). "We enrolled 628 adult asthmatic patients and 1:1 age-sex matched community-based controls in southern Taiwan and performed a combined effect sizes analysis to test if CHI3L1 polymorphisms were related to genetic risks for asthma in the Asian population." (PMID 25056157, 2014). "They concluded that rs103999331 and rs4950925 are equally likely to modulate CHI3L1 expression and susceptibility to asthma in Caucasian and African populations." (PMID 25056157, 2014). "Our findings suggest that CHI3L1 polymorphisms rs1538372 and rs10399931 can be used as genetic markers predicting asthma risk in the Taiwanese population." (PMID 25056157, 2014). "Our findings suggest that the CHI3L1 polymorphisms rs1538372 and rs10399931 can be used as genetic markers for predicting asthma risk in the Taiwanese population." (PMID 25056157, 2014). "A genome-wide association study uncovered Chitinase 3 like 1 (CHI3L1) as a candidate gene for asthma susceptibility." (PMID 25056157, 2014). "Following the discovery that CHI3L1 variation affects serum YKL-40 levels, the risk of asthma and impaired lung function were studied in Western European and American populations with a genome-wide association method." (PMID 25056157, 2014). "Further examination of expression patterns of the 101 gene signature in this comparison indicate that chi3l1, which is associated with asthma, was upregulated only in endotoxin exposed mice." (PMID 23675439, 2013). "CHI3L1 encodes the inflammatory protein YKL-40 and circulating levels of this protein are reported to be elevated in patients with respiratory inflammatory diseases such as asthma and sarcoidosis." (PMID 19568425, 2009).
asthma (continued). "In a genome wide association study CHI3L1 was found to be a susceptibility gene for asthma, bronchial hyperresponsiveness and reduced lung function." (PMID 19568425, 2009). "The objective of the present study was to investigate the association of common variation in the CHI3L1 locus with asthma, atopy and lung function in a large population-based sample of adults." (PMID 19568425, 2009). "Prevalence and risk (odds ratio (95% confidence interval))a of atopy, atopic asthma and self-reported physician diagnosed asthma according to single nucleotide polymorphisms (SNPs) of CHI3L1." (PMID 19568425, 2009). "The objective of the present study was to investigate the putative association of common variation in the CHI3L1 locus with asthma, atopy and asthma quantitative traits including measures of lung function in a large sample of adults Danes." (PMID 19568425, 2009). "In conclusion, the present large population-based study investigated the associations of variations of CHI3L1 with asthma and atopy in unrelated adults." (PMID 19568425, 2009). "Furthermore, the A allele of rs4950928 was associated with higher serum CHI3L1 levels and severer asthma after the control of risk genotype (CC)." (PMID 38667293, 2024). "Elevated levels of CHI3L1(YKL40) in blood or sputum samples could potentially aid in identifying patients with a higher risk of severe asthma attacks, as well as guiding treatment decisions." (PMID 38543093, 2024). "Serum CHI3L1 was also associated with persistent asthma in obese asthma patients." (PMID 38667293, 2024). "Increased expression of YKL-40/CHI3L1 is positively associated with pathogenesis in allergic rhinitis, atopic dermatitis and food allergy and CHI3L1 SNPs confer risk of asthma development and airway remodeling as well as increased serum IgE and atopy." (PMID 37575256, 2023). "Correlations of CHI3L1 gene polymorphisms with asthma in previous studies have been inconsistent." (PMID 30988078, 2019). "A false-positive result may instead explain the modest association between CHI3L1 and late-onset asthma." (PMID 30940096, 2019). "In addition, due to the ambiguous results of different studies on the relationship between CHI3L1 polymorphisms and asthma, a meta-analysis was performed using data collected from previously published reports and the present study." (PMID 30988078, 2019). "Importantly, the dysregulated expression of Chi3l1 is also significantly associated with many of human diseases including asthma and various tumors." (PMID 29403003, 2018). "Most of the ongoing researches have been carried out on SNP rs4950928 in the promoter region of CHI3L1 gene as it was found to be associated with the serum/plasma YKL-40 levels and diseases such as asthma, bronchial hyperresponsiveness, and the severity of hepatitis C virus-induced liver fibrosis." (PMID 30498395, 2018). "After stratified according to ethnicity, CHI3L1 rs4950928 variant was associated with decreased asthma risk in Caucasians (GG + GC vs. CC: OR = 0.621, 95% CI = 0.484–0.797, P = 0.000; GC vs. CC: OR = 0.612, 95% CI = 0.470–0.796, P = 0.000; G vs. C: OR = 0.696, 95% CI = 0.567–0.856, P = 0.001)." (PMID 29233108, 2017). "In addition, Genetic studies have demonstrated that the polymorphic variants of CHI3L1 gene contribute to the pathogenesis of asthma through influencing on airway inflammation and airway remodeling in the asthmatic patients." (PMID 29233108, 2017). "Genetic studies have demonstrated that the variants of CHI3L1 may contribute to the pathogenesis of asthma." (PMID 29233108, 2017). "Therefore, our meta-analysis provided a more statistical estimation demonstrating the relationship between CHI3L1 rs4950928 polymorphism and risk of asthma." (PMID 29233108, 2017). "However, following subgroup analysis by ethnicity, there was a protective effect of CHI3L1 rs4950928 polymorphism on asthma risk in Caucasians." (PMID 29233108, 2017).